SNX24 (sorting nexin 24)
Description:
May be involved in several stages of intracellular trafficking.
Synonyms: SBBI31; PRO1284
Tractability: Antibody: UniProt places it where antibodies can reach, with medium confidence. PROTAC: ubiquitination databases record sites on it.
Gene: Protein-coding gene on chromosome 5 (122,843,439 to 123,029,354, forward strand). Ensembl gene ENSG00000064652.
Subcellular location: Cytoplasmic vesicle membrane
Subcellular location (Human Protein Atlas): Vesicles
Gene Ontology:
Molecular function: protein binding; phosphatidylinositol phosphate binding; phosphatidylinositol binding; phosphatidylinositol-3-phosphate binding; phosphatidylinositol-4-phosphate binding; phosphatidylinositol-5-phosphate binding
Cellular component: cytoplasmic vesicle membrane
Genetic constraint (gnomAD): Loss-of-function variants: 5 observed, 4.99 expected, observed/expected ratio (o/e) 1, 90% interval 0.51 to 1.81. That is too few expected variants to judge how well the gene tolerates losing a copy. Missense variants: 54 observed, 50.15 expected, observed/expected ratio (o/e) 1.08, 90% interval 0.86 to 1.35. Synonymous variants: 14 observed, 21.4 expected, observed/expected ratio (o/e) 0.65, 90% interval 0.43 to 1.02.
Homologues: Orthologues: pig SNX24 (100% identical), chimpanzee SNX24 (99% identical), dog SNX24 (99% identical), mouse Snx24 (97% identical), rabbit SNX24 (89% identical), rat Snx24 (89% identical), guinea pig SNX24 (86% identical), zebrafish snx24 (77% identical). Paralogues in human: SNX22 (49% identical).
Diseases named in the same sentence as SNX24 in open-access papers:
SNX24 is named in the same sentence as 9 diseases in open-access papers, as found by Europe PMC text mining. Sharing a sentence is not in itself a finding about the gene and the disease. The quoted sentences say what the papers report.
breast carcinoma (1 paper, 2013). "Estrogen has been found to significantly upregulate the expression of SNX24 in certain breast cancer cell lines, suggesting that it has a role in tumorigenesis." (PMID 24268062, 2013).
endothelial dysfunction (1 paper, 2013). In vascular diseases, endothelial dysfunction is a systemic pathological state of the endothelium (the inner lining of blood vessels) and can be broadly defined as an imbalance between vasodilating and vasoconstricting substances produced by (or acting on) the endothelium. "This is the first study to report that SNX24 is a regulator of vascular inflammation and may be beneficial for many inflammatory diseases associated with endothelial dysfunction." (PMID 24268062, 2013).
cancer (2 papers, 2016 to 2024). A tumor composed of atypical neoplastic, often pleomorphic cells that invade other tissues. "UNG, FUCA2, DERA, GMFB, TF, and SNX24 as significantly downregulated upon mir-145 over-expression, are expected to have elevated expressions in tumor samples considering low levels of miR-145 in several cancer types." (PMID 27655328, 2016). "We identified six genes including UNG, FUCA2, DERA, GMFB, TF, and SNX24 as significantly downregulated and two genes including MYL9 and TAGLN as significantly upregulated upon mir-145 over-expression in distinct cancer types." (PMID 27655328, 2016).
neurodegenerative disease (1 paper, 2023). A disorder of the central nervous system characterized by gradual and progressive loss of neural tissue and neurologic function. "The miR-124-3p enriched for three hubs (Gmcl1, Snx24, and Eif3l) of those modules negatively correlated with the HNS group and enriched for inflammatory pathways or neurodegenerative diseases." (PMID 37355705, 2023).
SNX24 also shares sentences with these, for which no sentence is quoted: bacteremia (1 paper); coronary artery aneurysm (1); coronary artery disease (1); Kawasaki disease (1); tumor (1).